MET (MET proto-oncogene, receptor tyrosine kinase)
Diseases named in the same sentence as MET in open-access papers (continued):
Sharing a sentence is not in itself a finding about the gene and the disease.
cancer (continued). "MET and AXL were shown to regulate cancer cell growth, migration, invasion, and drug resistance via altering MAPK/ERK, PI3K/AKT, and STAT3 signaling." (PMID 34766112, 2020). "Cancer cell functions such as migration, stemness and EMT were assessed in the collagen matrices upon exposure to HGF-neutralising antibody (Hi), or c-MET inhibitor (Ci) alone or in combination for longer periods of 4 weeks." (PMID 32203220, 2020). "MET inhibitors reduce proliferation, invasion, migration, and downstream signalling in gastric MET-amplified cancer cells, but overexpression of HGF in cancer cells impairs this phenomenon." (PMID 33271944, 2020). "The data of these datasets supports proposed interaction of HOTAIR and MET and they are very important to show similar results with HCC in different cancer and cellular contexts." (PMID 32650779, 2020). "Crosstalk between c-MET and epidermal growth factor receptor (EGFR) is involved in the progression of many types of cancers." (PMID 33217986, 2020). "It is fair to highlight that the PI3K/AKT pathway is often overactivated in cancer progression and that c-Src and PI3K can be recruited together after c-MET activation." (PMID 33212946, 2020). "Firstly, MET (HGF receptor, traditional receptor tyrosine kinase but with a novel regulatory function in cancer immunity) was chosen as a representative TIME factor." (PMID 33299118, 2020). "The activation of c-MET by HGF is well-known to induce cells viability and proliferation in many kinds of cancer cells." (PMID 32545325, 2020). "Activation of MET by HGF, and that of ALK by PTN or MK as its ligands, renders cancer more aggressive by activating multiple downstream pathways, including the PI3/AKT and ERK pathway." (PMID 32754598, 2020). "Gatekeeper or solvent front mutations frequently pose a liability for targeted kinase inhibitors, for example, ALK (ALKG1202R) and ROS1 (ROS1G2032R) recurrently arise in cancer patients treated with crizotinib, a type I ROS1/ALK/MET targeted TKI25,35,36." (PMID 33328556, 2020). "AT13387 exerted high activity against cancer cells addicted to several oncoproteins including receptor tyrosine kinases such as EGFR, ERBB2, c-MET (hepatocyte growth factor receptor) and FLT3 (Fms-related tyrosine kinase 3)." (PMID 31659567, 2020). "Analysis of single-cell RNA-seq data from GSE111672 revealed that both MET and RIPK2 were expressed in cancer cells while RIPK2 was also expressed in monocytes and neutrophils." (PMID 33204717, 2020). "MET inhibitors inhibit proliferation, invasion, migration, and HGF/MET downstream signaling in gastric MET-amplified cancer cells, but HGF overexpression in cancer cells impairs this phenomenon." (PMID 32435640, 2020). "Treatment with HGF-neutralising antibody + c-MET inhibitor (Hi + Ci), as well as gemcitabine in combination with HGF/c-MET inhibition (Hi + Ci + G) significantly increased apoptosis of cancer cells." (PMID 32203220, 2020). "Many ongoing clinical trials in a variety of cancers, in phases I, II, and III have employed MET kinase inhibitors or monoclonal antibodies for MET (MAbs such as Onartuzumab from Genentech)." (PMID 33271944, 2020). "Several studies have suggested the prognostic and predictive value of two receptor tyrosine kinases (RTKs), MET and AXL, as biomarkers and potential therapeutic targets in cancer treatment." (PMID 34766112, 2020). "As we can see from the scatter plots, both MET and RIPK2 are expressed in cancer cells, confirming the necessity to research their role in the development of PDAC." (PMID 33204717, 2020). "Compared with normal tissue, the expression level of MET was downregulated in BRCA, LAML, and LGG and upregulated in 20 types of cancers including CESC, COAD, and PAAD." (PMID 33299118, 2020).
cancer (continued). "In order to further research the mechanism of how MET and RIPK2 promote the progression of PDAC, we predict that the role of these two genes in cancer is to promote autophagy and took these two genes as central nodes to construct a probable regulatory network." (PMID 33204717, 2020). "Our in vitro 3D culture studies supported our in vivo observations for HGF + c-MET inhibition on EMT, with cancer cells expressing a significant increase in E-cadherin and a significant decrease in vimentin in this treatment group." (PMID 32203220, 2020). "As we can see from scatter plots and bubble plots, both MET and RIPK2 were expressed in cancer cells and epithelial cells." (PMID 33204717, 2020). "We have recently found that SEMA3C drives cancer growth by transactivating multiple receptor tyrosine kinases including EGFR, HER2 and MET via Plexin B1." (PMID 30759745, 2019). "Our method can not only prioritize the significant cancer driver genes but also identify some potential cancer driver genes which were neglected by the NCG 4.0 such as the NES, MET and HGF." (PMID 31888619, 2019). "Several MET targeting-MKI and specific MET kinase inhibitors have entered clinical trials in various cancers with MET alterations." (PMID 31040922, 2019). "Here, we report that activation of the MET/FAK signalling axis leads to CDK4/6-independent CDK2 activation, and constitutes a broadly applicable druggable means to improve the response of cancers to CDK4/6-targeted therapies." (PMID 31296956, 2019). "Various cancers have aberrant RON and MET expression and activation, which contribute to cancer cell proliferation, invasiveness, and metastasis." (PMID 31867280, 2019). "Examples of RTKs that frequently have alterations in cancer cells, and therefore are constitutively providing oncogenic signals, are VEGFR, EGFR, HER2 and c-MET (hepatocyte growth factor receptor)." (PMID 31695800, 2019). "Functional cross-talk of MET with other RTKs, such as EGFR, HER2, HER3, RET or IGF1R, was identified in various cancers as mediating inhibitors resistance." (PMID 31040922, 2019). "In human cancer, the RTKs RON, MET, and EGFR are frequently co-expressed and promote resistance to targeted therapeutics." (PMID 31867280, 2019). "Coordinated recyclings of MET, EGFR, and other RTKs with Integrins through Rab11-FIP1 have been suggested to play a pivotal role in promoting cancer invasion." (PMID 31595389, 2019). "Due to the fact that cancer cells resistant to treatment often display overexpression of growth factor receptors, we checked the level of EGFR and MET in generated cell lines." (PMID 31877948, 2019). "This suggested that MET and STAT3 are important oncogenes in LINC00857 regulating cancer progression in EAC cells." (PMID 31085800, 2019). "Both the kinase MET and the WNT signaling pathway are attractive targets in cancer therapy, and synergistic effects have previously been observed in animal models upon simultaneous inhibition." (PMID 35539091, 2019). "In contrast, several agents, such as cabozantinib (VEGFR, MET, RET), ABT-888 (PARP), dabrafenib (BRAF), imatinib (Bcr/Abl), and sunitinib (PDGFR), demonstrated relatively minimal anti-cancer activities." (PMID 31771620, 2019). "Actually, there are many other primary resistance mechanisms, include amplification of the MET gene, EMT, and cancer stem cell-like cells, contributing to the resistance to EGFR TKIs." (PMID 31138318, 2019). "Cabozantinib is a newly developed small molecule inhibitor of the tyrosine kinases c-MET and VEGFR2 that is used to treat medullary thyroid cancer and a first-line treatment for advanced RCC, amongst other cancer types." (PMID 35582714, 2019). "Neutrophils, expressing the hepatocyte growth factor receptor c-MET, inhibit growth of several cancer types, through the release of tumor necrosis factor α (TNFα) and nitric oxide (NO)." (PMID 31461847, 2019).
cancer (continued). "Tivantinib (ARQ 197), a novel and highly selective non–ATP-competitive MET inhibitor, can inhibit human recombinant MET with a calculated inhibitory constant (Ki) of ~355 nM, and is currently in phase III cancer clinical trials." (PMID 31867280, 2019). "We have observed that the cancer cell invasion of both U373-MG and LN229 cells were effectively suppressed by either the biotin-conjugated goat anti-MET antibodies or the APC-conjugated mouse anti-MET antibodies." (PMID 30760737, 2019). "Increased understanding of cancer biology has led to the development of anticancer drugs targeting specific oncogenic substrates such as AKT, BCR-ABL1, EGFR, MET, and the IGF-IR." (PMID 31269742, 2019). "Along with MET induction, etoposide attenuated glycosylated PD-L1 expression and PD-1 binding ability of sphere cells, and sensitized sphere cells to PBMC-mediated cancer cell killing in vitro." (PMID 29765039, 2018). "Recent reports show that several microRNAs participate in inhibiting HGF/c-MET signaling networks through antagonizing c-MET or HGF in digestive system cancers, and the miRNAs-HGF/c-MET axis plays crucial and novel roles for cancer treatment." (PMID 30360560, 2018). "However, no c-MET mutations have been reported so far in these cancers." (PMID 30159127, 2018). "Cell type-specific Exo proteins are so far most comprehensively explored for cancer and cancer stem cells (CSC), such as MART1, EGFRVIII, multidrug resistance gene 1, EpCAM, MET, mutant KRAS, and tissue factor." (PMID 29456536, 2018). "Unfortunately, the same highly regulated events that mediate MET/HGF biological responses during embryo development and contribute to maintain tissue homeostasis in the adult are unleashed in cancer." (PMID 30544501, 2018). "In this study, we demonstrate that TGFβ signaling leads to increased MET signaling activity and that this results in HGF‐dependent migration of breast epithelial and cancer cells." (PMID 30004628, 2018). "In cancer tissue, activation of HGF/MET signaling axis occurs mainly by paracrine fashion, and several cancers express HGF, which leads to autocrine-loop-style MET activation." (PMID 30469509, 2018). "For all other hallmarks of cancer features promising prognostic biomarkers were identified as well, including COX-2, PAK-1, p14ARF, MET, LC3B, IGFBP7 and LGR5." (PMID 30185893, 2018). "B1SP is a multi‐RTK pathway inhibitor targeting EGFR, MET, and HER2/ErbB2 and has potential clinical utility for a number of cancers wherein these RTKs are clinically validated targets including lung, breast, and colorectal cancers." (PMID 29348142, 2018). "The strong anti-cancer effects of (S)-crizotinib in inhibiting GC cell growth likely indicate that these cells harbor alterations of ALK, ROS1, and or MET, although their precise genomic profile remains to be determined." (PMID 29855474, 2018). "By abolishing c-MET activation by fibroblast using DCC2701, a c-MET/TIE-2/VEGFR inhibitor, the cancer growth and migration was subsided." (PMID 29455663, 2018). "Additional biomarkers currently being studied for application in cancer treatment include the PIK3CA, HER2, BRAF, ROS, RET, NRAS, MET, and MEK1." (PMID 29721208, 2018). "MET signaling in GC is related to worse prognosis, because HGF/MET activity is involved in cancer growth, invasion, angiogenesis, and epithelial-to-mesenchymal transition." (PMID 30205505, 2018). "Membrane receptor tyrosine kinases, e.g. EGFR, FGFR, IGF1-R, MET, AXL, KIT, RON, VEGFRs and PDGFRs1, have become important targets for cancer precision therapy." (PMID 29728634, 2018). "Of interest, phosphorylation of MET and expression of HAI-1 were observed reciprocally in cancer tissues." (PMID 30469509, 2018). "For the MET-, IGFBP7, and LGR5 pathways targeted therapies have already been studied in other cancer types with varying results, however, the potential to target these biomarkers in EAC is yet to be investigated." (PMID 30185893, 2018).
cancer (continued). "MET, a transmembrane tyrosine kinase receptor for hepatocyte growth factor (HGF), has been observed to contribute to cancer metastasis, resistance to chemotherapeutic agents, and dismal outcomes of patients with solid cancers including HCC." (PMID 29712569, 2018). "Collectively, our results demonstrated that the NRF2 silencing-inducible miR-206 targeted both c-MET and EGFR, and subsequently suppressed the BCRP level in cancer cells." (PMID 29291022, 2017). "Autophosphorylation of MET leads to the activation of a number of downstream pathways (PIK3, Akt, and RAS-MAPK) responsible for cancer cell survival, proliferation, invasion, and metastasization." (PMID 29094049, 2017). "Cancer cell lines dependent on known receptor tyrosine kinases (such as EGFR, ERBB2, c-MET, and FLT3) were found to be sensitive to SHP2 depletion." (PMID 29371942, 2017). "MET activation triggers Ras-dependent ERK1/ERK2 activation and STAT3 signaling, which contribute to enhanced proliferation, survival and migration of cancer cells." (PMID 28420162, 2017). "To elucidate this, we examined the expression of c-MET and EGFR levels in NRF2-silenced cancer cells." (PMID 29291022, 2017). "MET increased the expression of FZD8 via the ERK/c-Fos cascade in the cancer stem-like cells (CSC) of head and neck squamous carcinomas (HNSCC), and Wnt pathway receptor FZD8 was necessary for interplay between MET and Wnt/β-catenin signaling." (PMID 29108281, 2017). "Crizotinib treatment also decreased the level of several cancer protein biomarkers, including CA724, CA199 and CA242, plasma concentration of total cell free DNA (cfDNA) and MET relative copy number." (PMID 28460431, 2017). "In contrast, targeted therapeutic agents, which block individual pathways that cancer cells are addicted to (such as EGFR, BRAF, MET or HER2 signaling), are specific for cancer cells and have potentially fewer side effects." (PMID 28420162, 2017). "Altogether, these data show that in MET‐addicted carcinoma cell lines, HSP27 silencing affected cell survival and allowed MET inhibitor to exert a full cytotoxic effect." (PMID 28182330, 2017). "Aberrantly activated MET/HGF signaling correlates with tumorigenesis and metastasis, and is regarded as a robust target for the development of novel anti-cancer treatments." (PMID 27013592, 2016). "MET also known as c-Met or hepatocyte growth factor receptor (HGFR), is an RTK with deregulated function in certain types of cancer." (PMID 27486382, 2016). "However, based on reported MET gene amplification and overexpression prevalence, discrepancies clearly result from the use of different detection methods, the number of patients enrolled in a given study, the use of different scoring systems and differences in cancer types." (PMID 27013592, 2016). "Next, we used FISH to determine the absolute copy number at loci harboring cancer-relevant genes: ALK, ROS1, MET, BRAF and RET." (PMID 27100738, 2016). "Restoration of mature miR-206 inhibited cancer cell proliferation, migration, and invasion in human lung SCC cell lines through down-regulation of both mRNA and protein levels of MET and EGFR." (PMID 26646588, 2016). "Because of its pleiotropic role in oncogenesis and cancer progression, HGF/c-MET is considered to be an important target in anticancer therapy." (PMID 27923392, 2016). "Sorafenib also inhibits cell migration and invasion through suppression of EMT, c-MET, and MAPK pathways in different cancer cells." (PMID 26517521, 2016). "The authors observed MET staining in stromal cells within several cancers and demonstrated that the MET4 antibody correlated more strongly with active MET (phosphorylated MET) than other MET antibodies." (PMID 27655711, 2016). "We demonstrated that inhibitors of HGF activation such as SRI 31215 represent a novel approach to inhibit autocrine and paracrine oncogenic HGF/MET signaling and to prevent HGF-dependent proliferation, EMT and migration of cancer cells." (PMID 27121052, 2016).
cancer (continued). "Interactions between MET and other RTKs, including RON, PDGFR, Axl, HER2, ERBB3 and VEGFR family members, have been observed in a variety of cancers." (PMID 27013592, 2016). "Several cancers are addicted to HGF/MET signaling, establishing both HGF and MET as valid therapeutic targets." (PMID 27121052, 2016). "Studies have demonstrated that sorafenib induces apoptosis in cancer cells by targeting PDGFR, FGFR, c-KIT, MET, MAPK and other signaling pathways." (PMID 26517521, 2016). "MET activation promotes the cancer stem cell phenotype and HGF/MET signaling plays a crucial role in the development of resistance to classical cytotoxic therapy and targeted therapy, such as EGFR and BRAF inhibitors." (PMID 27121052, 2016). "In various cancer cell lines, MLK3 has been shown to signal through multiple receptors including EGFR, hepatocyte growth factor (HGF) receptor, more commonly known as c-MET, and Discoidin domain receptor 1 (DDR1)." (PMID 27213454, 2016). "The HGF-activating proteases are upregulated and the levels of HAI-1/2 are reduced in cancer tissues, resulting in increased activation of HGF and constitutive stimulation of HGF/MET signaling." (PMID 27121052, 2016). "c-MET and epidermal growth factor receptor (EGFR) are well-known tyrosine receptor kinases that are coexpressed in multiple cancers, including GBM." (PMID 26700818, 2016). "Because some client proteins (e.g., HER2, BRAF, and MET) play an important role in tumorigenesis, HSP90 is considered as a druggable target for cancer treatment." (PMID 27409672, 2016). "Compound 13b showed the most potent inhibitory activity against c-MET with IC50 of 0.02 μM, and it exhibited good anticancer activity against tested cancer cell lines." (PMID 27187326, 2016). "Thus, MET may represent a promising target for cancer therapies." (PMID 27013592, 2016). "Mechanistic studies show that CUDC-101 integrates HDAC and EGFR/HER2 pathway inhibition, blocks and inhibits MET- and AXL-mediated signaling, and reduces cancer cell migration." (PMID 25940539, 2015). "These include MET, which has been shown to heterodimerize with AXL to regulate cancer cell migration/invasion." (PMID 26356563, 2015). "The small molecule kinase inhibitor T-1840383 inhibits both HGF-induced c-MET phosphorylation and VEGF-induced VEGFR-2 phosphorylation in cancer epithelial cells and vascular endothelial cells, respectively." (PMID 28536400, 2015). "In vitro studies of MET and EGFR have shown that a single amplified receptor tyrosine-kinase can determine growth and survival of different cancer cell lines (lung, gastric)." (PMID 26319934, 2015). "We next examined the effects of adding growth factors to the culture medium of cancer cells and the effects of FGFR inhibitor and MET inhibitor treatment on cell proliferation induced by fibroblast supernatant." (PMID 25884729, 2015). "Initial results from most studies suggest that anti-MET therapy is able to improve overall survival (OS) and progression-free survival (PFS) in several cancer types." (PMID 26528757, 2015). "In this review, recent progress in HGF/MET pathway-targeted therapy for cancer treatment, the therapeutic potential of HGF/MET-targeted agents, and challenges in the development of such agents will be discussed." (PMID 28536405, 2015). "In the simulations, we focused only on CD44, CD47 and MET overexpressions and underexpressions (excluding EPCAM) because we are considering the cancer cells that are already in the blood vessels." (PMID 25978366, 2015). "Previous studies showed that miR-34a targets the oncogenes CDK4, CDK6, CCND1, MET, and BCL2, whereas miR-497 targets the oncogenes CCND2 and BCL2 in various types of cancer." (PMID 25909221, 2015). "Cabozantinib also inhibits MET and VEGFR2, two RTKs believed to play major roles in the growth and dissemination of cancer cells." (PMID 25388653, 2014).